EGFR (epidermal growth factor receptor)
Diseases named in the same sentence as EGFR in open-access papers (continued):
Sharing a sentence is not in itself a finding about the gene and the disease.
cancer (continued). "The importance of EGFR/β1 integrin cooperation in radiotherapy resistance has been confirmed by experiments which have shown that co-targeting the two of them radiosensitizes cancer cells." (PMID 31109009, 2019). "One of the main pathways that are commonly altered in cancer is the EGFR/ERK pathway." (PMID 31157216, 2019). "Anti-EGFR treatments can induce protective autophagy in several cancer cell lines and solid tumors." (PMID 31527477, 2019). "The role of EGFR signaling in the pathogenesis of cancer, including the lung, is undisputable." (PMID 31438559, 2019). "- Targeting EGFR's kinase independent functions may overcome cancer resistance to current EGFR inhibitors." (PMID 31508364, 2019). "Motivated by all these findings, we have designed and synthesised a series of pyrazolo[3,4-d]pyrimidines as novel small molecules targeting both EGFR and ErbB2 tyrosine kinases to be useful for treatment of cancer via inhibition of cell growth and induction of apoptosis." (PMID 30688116, 2019). "Moreover, BDNF cross-activated TrkB and EGFR in cancer cells expressing both receptors, suggesting a novel cooperative interaction between these signaling pathways in TNBC." (PMID 30796353, 2019). "Moreover, the C‐dots disrupt likely through nucleotide excision DNA repair at low dose during DNA ligation step suggesting the antimicrobial effect and targeting Pim‐1, EGFR, mTOR, and DNA damage pathways in cancer cells." (PMID 31692950, 2019). "Moreover, the effects of those inhibitors on downstream signalling in cancer cell lines harbouring BRAF, KRAS, or EGFR mutations were evaluated to assess the relationship between dimerization and paradoxical activation." (PMID 30679688, 2019). "This retrospective study evaluated real-world treatment patterns of patients with advanced EGFR Mut+ NSCLC in oncology practices across the USA, and examined demographic and disease characteristics among patients receiving EGFR TKIs vs other systemic anti-cancer therapies." (PMID 30608948, 2019). "However, cancer cells can activate alternative signaling pathways, such as EGFR, AKT, and mTOR, to maintain cell proliferation under Sorafenib treatment." (PMID 31615983, 2019). "One approach to treating these cancers is with drugs that block the activity of mutant EGFR." (PMID 31741433, 2019). "Further data supporting this hypothesis could be gained from investigating muscle ST fiber proportion in patients receiving EGFR inhibitor treatment for cancer." (PMID 31239465, 2019). "On one hand, protein levels of EGFR, but not its phosphorylation status, is strongly associated with disease progression and poor prognosis of many types of cancers that rarely express mutated EGFR." (PMID 31508364, 2019). "For instance, co-treatment of EGFR inhibitor Gefitinib or anti-CD47 antibody could effectively improve the anti-cancer effect of Sorafenib in the mouse models." (PMID 31615983, 2019). "Because YM155, an interleukin enhancer-binding factor 3 (ILF3) inhibitor, can block EGFR autophosphorylation to inhibit G9a-mediated stemness, EGFR downstream of G9a may also regulate cancer stemness and HER3 expression." (PMID 31619200, 2019). "Importantly, EGFR inhibitors significantly reduced the number of residual cancer cells after cytotoxic anticancer drug treatment and enhanced the antitumor effect of irinotecan in vivo." (PMID 31607750, 2019). "We suggest that efforts to more clearly confirm or identify the direct receptor of SPINK1, and the mechanism by which it influences EGFR signaling, could lead to identification of novel points for therapeutic intervention in cancers that express SPINK1." (PMID 30778387, 2019). "Quercetin has been shown to inhibit cancer cell growth through targeting EGFR in HNC cancer cells." (PMID 31139565, 2019). "As EGFR is highly expressed in many human cancers, it might stabilize aberrant ER-endosome MCSs to sustain endosomal signaling and prevent signaling termination by lysosomal degradation." (PMID 32039198, 2019).
cancer (continued). "In addition, cancers expressing wild-type EGFR (wt-EGFR) are often insensitive to TKIs, although TKIs are potent in inhibiting the kinase activity of wt-EGFR as well." (PMID 31121829, 2019). "EGFR inhibitors have produced impressive therapeutic benefits to responsive types of cancers." (PMID 31508364, 2019). "However, details about the mechanism by which BZW1 regulates EGFR activity in cancer still needs further investigation." (PMID 31601833, 2019). "We asked whether PD‐L1 upregulation by paracrine AREG is subject to intracellular signaling that involves EGFR, its downstream factors, or other molecules in recipient cancer cells." (PMID 31493351, 2019). "Furthermore, the model showed excellent transferability across different cancer cell lines and EGFR inhibitors, including gefitinib, erlotinib, afatinib, and cetuximab." (PMID 30621238, 2019). "Additionally, our studies and others have further investigated the EGF/EGFR-mediated tyrosine phosphorylation of Grb7 that is involved in aggressive and malignant features of cancers." (PMID 31083325, 2019). "Furthermore, genetic alterations of the EGFR gene result in a common cancer-associated variant III (EGFRvIII), in several cancers." (PMID 30970654, 2019). "Therefore, the cancer-associated mutations in PLC-γ1 were further tested for effects on lipase activity after co-expression of PLC-γ1 and EGFR." (PMID 31889510, 2019). "The epidermal growth factor receptor (EGFR/HER1) may be the most well-known protein that is overexpressed in cancers, and for which several monoclonal antibodies and small-molecule inhibitors exist." (PMID 31505803, 2019). "Simultaneously, the results of the inhibition of transwell and tube formation proved that L14e could inhibit the activation of the EGFR signaling pathway and ultimately achieve the purpose of inhibiting cancer cell migration and angiogenesis." (PMID 31296849, 2019). "EGFR inhibitors, such as gefitinib and erlotinib, are in the clinic as cancer treatments." (PMID 31239465, 2019). "Pyk2 could regulate AKT, STAT3, ERK, MEK1/2, Src, HER3, MAPK, EGFR, and STAT5b in EGFR signaling in different cancer types." (PMID 31368612, 2019). "Interestingly, our results demonstrated that KP markedly reduced EGF-induced Mcl-1 production in HeLa cells, confirming its anti-cancer ability to modulate the EGFR/MAPK signaling cascade." (PMID 31470515, 2019). "Elevated levels of nuclear EGFR correlate with poor prognosis in various cancers." (PMID 31426451, 2019). "In the future, 18F-AlF-NOTA-ZEGFR:03115 could also be used for the identification of residual EGFR-positive cells that may be responsible for subsequent cancer relapse." (PMID 30213849, 2019). "One explanation to it is that, in these scenario, the KID oncogenic function of EGFR might be enhanced by TKIs and thus survivability of cancer cells, which hampers the cytotoxic effect of the chemotherapeutics." (PMID 31508364, 2019). "Our model implies that combining GR modulation to EGFR inhibition may yield an effective treatment strategy in halting cancer progression." (PMID 31052457, 2019). "A recent experience demonstrated that genomic analysis is highly informative for some cancers with targetable mutations (e.g., BRAF and EGFR), but remains insufficient to identify effective therapeutic options for the majority of patients with advanced cancers, including PDA." (PMID 31195689, 2019). "Moreover, EGFR is expressed in many normal epithelial tissues and in many human cancers, including those of colon and rectal." (PMID 30930778, 2019). "Additionally, exosomes can efficiently deliver microRNAs, such as let-7a, to breast cancer cells overexpressing EGFR, inhibiting cancer development in vivo." (PMID 31078138, 2019). "The saga of erlotinib in EGFR activating mutation negative cancer started with the publication of BR.21 results." (PMID 31695838, 2019).
cancer (continued). "Cancer cells that overexpress EGFR or HER2 are particularly sensitive to DDAs2,4." (PMID 31839995, 2019). "A number of EGFR signaling pathways have been linked to NFκB activation downstream of ligand stimulation or constitutive EGFR activation in cancer cells, primarily by promoting degradation of inhibitor of kappa B (IkB) proteins that sequester inactive NFκB proteins in the cytoplasm." (PMID 31425554, 2019). "In summary, our data together pinpoint the crucial role of glycolysis and resultant lactate production, which fuels the TCA cycle for energy production in FGFR aberrant cancer, and the serine synthesis for nucleotide biosynthesis and redox homeostasis in EGFR constitutively activated cancer." (PMID 31221965, 2019). "Together, our data consistently suggested that either controlling EGFR as a plasma membrane receptor on recipient cells or targeting AREG as a soluble factor from damaged stromal cells can significantly deprive cancer cells of acquired resistance to chemotherapeutic agents." (PMID 31493351, 2019). "The combined use of approved Janus kinase and EGFR inhibitors could be a new strategy for the treatment of cancer patients." (PMID 31013819, 2019). "Aberrant activation of the EGFR signaling pathway is critical for cancer cell apoptosis, proliferation, differentiation, and motility via the downstream RAS/RAF/MEK/ERK and AKT/PI3K/mTOR pathways, and tremendous amounts of research have implicated EGFR as a potential target for cancer therapy." (PMID 31608236, 2019). "Therefore, innovative therapeutic methods to reverse the EGFR inhibitors resistance and enhance the anti-cancer effect of NSCLC are highly desirable." (PMID 31316001, 2019). "In line with the previous report indicating that loss of EGFR protein but not its tyrosine kinase activity sensitized cancer cells to chemotherapeutic agent, EGFR tyrosine kinase inhibitors did not produce therapeutic effects for certain cancers." (PMID 31199048, 2019). "Since our data suggests that modest EGFR blockade modifies muscle phenotype, lower, and hence more tolerable, doses than those used in cancer treatment regimens (which aim for total downstream signaling blockade) may be efficacious in COPD patients." (PMID 31239465, 2019). "Furthermore, PCNDs have been functionalized with cetuximab (C225-PCNDs) for targeting cancer cells overexpressing EGFR." (PMID 31182936, 2019). "The EGFR has been reported as an attractive target for cancer therapy." (PMID 30769844, 2019). "Therefore, inhibiting the growth of cancer cells by EGFR signaling inhibition is one of the current treatment strategies for OSCC." (PMID 31750253, 2019). "Integrin-dependent FAK activation decreased cancer cells’ sensitivity to anti-EGFR drugs." (PMID 31109009, 2019). "Those carcinomas are EGFR-dependent in their survival and growth." (PMID 30854333, 2019). "Carcinomas expressed EGFR in 22 (66.67%) of 33 specimens and PTEN in 7 (21.21%) specimens." (PMID 30863440, 2019). "However, SQ20B tumors exhibited intermediate sensitivity to anti-EGFR therapy, with accelerated regrowth at the end of treatment (positively stained carcinoma cells remained after treatment)." (PMID 31640284, 2019). "Furthermore, a shotgun proteomic platform has been employed to analyze stimulation and inhibition of EGFR by EGF and gefitinib and cetuximab EGFR inhibitors, respectively, on the A431 human epithelial carcinoma cell line as model system." (PMID 31557914, 2019). "EGFR is expressed in several carcinomas and induces cellular transformation." (PMID 30854333, 2019). "Indeed, changes in EGFR expression and autoantibodies to this receptor have been observed in patients with SSc, nevertheless there is evidence for the involvement of EGFR signaling in the development of different carcinoma types." (PMID 30866419, 2019). "EGFR which transmits cell growth signals, plays significant role in cancer development." (PMID 30774817, 2018).
cancer (continued). "No cancer-associated EGFR gene mutation or copy-number variation, nor any KRAS, BRAF, NRAS hotspot mutations were found in any microdissected area." (PMID 29492209, 2018). "Some of these limitations can be overcome by the application of bispecific antibodies that can spontaneously bind to both the poly ethylene glycol (PEG) coated nanoparticles and cancer specific antigens such as prostate specific membrane antigen (PSMA) or epidermal growth factor receptor (EGFR)." (PMID 30116191, 2018). "EGFR represents an important target since it is often dysregulated in human cancers." (PMID 30279968, 2018). "EGFR signaling pathway plays a key role in cancer cell survival, growth and metastasis." (PMID 30618758, 2018). "Thus, the cooperation between TGF‐β and EGF/EGFR signaling pathways is likely beneficial to cancer progression." (PMID 29215776, 2018). "Another hub gene EGFR is widely recognized for its important role in cancer." (PMID 29983747, 2018). "EGFR is one of the most commonly oncogene overexpressed in many cancers, including ESCC." (PMID 30131072, 2018). "Mutations or overexpression of EGFR is often found in various human cancers, including non-small-cell lung cancer (NSCLC)." (PMID 29765556, 2018). "This novel cancer-promoting function of phosphorylated Fas in the nuclear EGFR signaling constitutes the foundation for developing pro-survival-Fas targeted anti-cancer therapies to overcome disease recurrence in patients with anti-EGFR resistant cancer." (PMID 30127519, 2018). "Alterations in EGFR signaling can lead to apoptosis or enhanced proliferation, angiogenesis and necrosis, suggesting a strong correlation between dysregulated receptor activity and the pathobiology of many cancers." (PMID 29857516, 2018). "This disrupted degradation of EGF/EGFR could lead to prolonged EGFR signaling in endosomes, which may impact cancer cell proliferation." (PMID 29303993, 2018). "In addition, it has already been observed that irradiation treatment results in an increase in EGFR expression on cancer cells." (PMID 29603584, 2018). "Several EGFR TKIs are currently available for cancer treatment." (PMID 30404198, 2018). "We believe the cooperation of p120ctn down-regulation and EGFR overexpression is not only important in the aggressive mechanisms of ESCC but could be broadly applicable to many other cancer types in which p120ctn and EGFR are involved." (PMID 29541406, 2018). "Given the strong correlation of aberrant Src function with EGFR-Ras activation in human cancers, the finding that JNK and PI3K are critical mediators of Src–Ras cooperative tumourigenesis may provide specific targets for cancer therapy." (PMID 29861494, 2018). "Elevated expression and activity of EGFR protein and its phosphosites across cancer types suggest that phosphoproteome analysis may inform treatment response." (PMID 30053901, 2018). "As an oncogene, EGFR has long been proposed as a drug target for cancer treatment." (PMID 30514230, 2018). "In addition to cell proliferation, EGFR signaling contributes to progenitor cell migration and cancer dissemination." (PMID 30510261, 2018). "Trafficking of EGFR to the plasma membrane through AGR2-dependent catalysis in cancers might also be important for its' oncogenic function because AGR2-negative cells fail to localize EGFR to its membrane destination." (PMID 29339412, 2018). "Interestingly, nuclear EGFR signaling has been shown to promote DNA repair in cancer cell line models, and through this mechanism, it confers radio-resistance." (PMID 30018330, 2018). "These agents target T790M, re-sensitizing cancer cells to EGFR TKI inhibition." (PMID 30404198, 2018).
cancer (continued). "Inhibitors of EGFR activation, using monoclonal antibodies or small-molecule inhibitors, have been established successfully and are increasingly being used in first or later line cancer therapy." (PMID 30301942, 2018). "In this study, the chips using cetuximab could sufficiently recover the cancer cells with an EGFR expression level more than that of KYSE140 (6.0 × 104 receptors/cell)." (PMID 30104638, 2018). "In our study, we investigated whether blocking the interaction of Eps8 with EGFR could have a biological effect in cancer cells." (PMID 29515106, 2018). "First-line chemotherapy in EGFR-mutant NSCLC may decrease numbers of cancer cells, and diminish the overall clinical benefit of subsequent EGFR-TKI therapies." (PMID 29695969, 2018). "Depending on the retargeting module, the virus could be retargeted to cancer cells such as A431, expressing EGFR, or SKOV3.ip cells, expressing HER2." (PMID 29386504, 2018). "Therefore, HDAC3 can target CAGE to regulate the activation of EGFR signaling, responses to various anti-cancer drugs, and the tumorigenic potential of cancer cells." (PMID 30583572, 2018). "In addition, the activated NF-κB provides a positive feedback to regulate EGFR/Akt/mTOR pathway, thereby promoting the cell proliferation in cancers such as HNSCC." (PMID 29381751, 2018). "Together, these results indicate that intracellular EGFR may play an essential role in cancer metastasis and a potential mechanism for the failure of therapeutic antibodies in EGFR-driven metastatic breast cancer." (PMID 29464085, 2018). "We were able to extract DNA and perform an exploratory analysis of the cancer gene mutational status on archival biopsy samples from 11 of 16 patients and did not detect EGFR, KRAS or ALK gene alterations in any cases." (PMID 30647837, 2018). "In addition to cytokines, extracellular enzymes such as matrix metalloproteinases (MMPs) which are secreted by cancer cells under control of AP-1 play a role in Fra-1 induction in the same cells through activation of EGFR." (PMID 30344941, 2018). "NSCLC cancer cells are characterized by the aberrant activation of EGFR, ALK, or cMet27." (PMID 29449529, 2018). "Indeed, EGFR is one of the returned therapeutic bullets and represents a direct inhibition of EGFR, a well-studied target in cancer therapies." (PMID 29515890, 2018). "EGF significantly induced STAT3 phosphorylation and elevated the mRNA levels of LGR5 in the HT29 cells, implying that addition of EGF activated STAT3 in the cancer stem-like tumorspheres, thus contributing to the formation and survival of EGFR-positive CRC stem-like tumorspheres." (PMID 30068339, 2018). "Although classically thought of as epithelial specific molecules that regulate EGFR signaling via an autocrine loop, production of EREG and AREG has been detected in stromal cells including normal and cancer associated fibroblasts and various immune cell populations." (PMID 30412601, 2018). "Mutations of EGFR and KRAS are regarded as primary genetic “driver” leading to cancer." (PMID 30680072, 2018). "EGFR and its family members are the main components of a complex signaling cascade that regulates proliferation, growth, migration, differentiation, and survival of cancer cells." (PMID 30643798, 2018). "Thus, the development of small molecular compounds to inhibit EGFR is an important therapeutic approach for treating variety of cancers." (PMID 30563058, 2018). "In several cancer cells overexpressing ErbB2, inhibition of ErbB2 alone by specific inhibitors seems to be impossible since it is well known that ErbB2 is the preferential partners of the ErbB receptors, including EGFR." (PMID 29662626, 2018). "We examined here whether GLUT1 is also involved in the control of gefitinib resistance in the cancer stem cell subpopulation of EGFR-wt NSCLC cells." (PMID 30220973, 2018).